ADAM17 (ADAM metallopeptidase domain 17)
Diseases named in the same sentence as ADAM17 in open-access papers (continued):
Sharing a sentence is not in itself a finding about the gene and the disease.
colon carcinoma (continued). "Intriguingly, all three colon cancer-associated mutants (E319G, E406X, M435I) showed diminished enzymatic activity on the cell surface comparable to the mock control, whereas the pancreatic cancer variant P417Q exhibited peptide cleavage even above ADAM17 wild type level." (PMID 33143292, 2020). "Further studies with large sample size remain warranted to analyze the potential molecular mechanisms of specific tetraspanins regulating ADAM17 assembly in colon cancer cells." (PMID 38413999, 2024). "WT (ADAM17fl/flLck-Cre-) and ADAM17 KO (ADAM17fl/flLck-Cre+) mice were inoculated with colon cancer cells MC38 followed by intratumoral injection of sumIL-2." (PMID 38918390, 2024). "It has been previously reported that NOX1 interacts with ADAM17 and protects it from ubiquitin-mediated degradation in human colon cancer cells." (PMID 38137406, 2023). "The results showed that knockdown of HDAC6 inhibited phosphorylation of TAK1, p38, and ADAM17 in colon cancer xenograft mouse model, which were consistent with results in vitro." (PMID 36270986, 2022). "Since the majority of sIL-6R is derived from proteolysis mediated by the metalloprotease ADAM17, we knocked down ADAM17 with siRNA to verify its regulatory effect on sIL-6R release in colon cancer cells." (PMID 36270986, 2022). "Colon cancer cell-derived exosomal ADAM-17, a catabolic integrin and metalloproteinase, promotes colon cancer metastasis by cleaving E-cadherin junctions and participating in the formation of premetastatic niche." (PMID 36275738, 2022). "In recent years, the membrane-bound metalloprotease ADAM17 (a disintegrin and metalloprotease 17) has been identified as a key player in the development of colon cancer." (PMID 33143292, 2020). "Endogenous ADAM17 was removed using CRISPR/Cas9 technology in the colon cancer cell line DLD‐1 allowing for functional complementation with exogenous ADAM17 (Fig EV4C–F)." (PMID 32400009, 2020). "Summarizing, we propose crucial importance of the pro-domain on enzyme maturation and function and suggest ADAM17 as a modulator in colon cancer by its importance in inflammatory events, which have been shown to mediate tumorigenesis." (PMID 31060243, 2019). "In human colon tumor tissues, it was shown that the expression and activity of ADAM17 was significantly increased as compared with normal tissue, underlining an important role of ADAM17 in mediating the IL-6 trans-signaling response via the sIL-6R." (PMID 31694340, 2019). "Subsequently, IL-6 together with the ADAM17 shed soluble IL-6 receptor acts on intestinal epithelial cells via IL-6 trans-signaling to induce colon cancer formation, which can be blocked by the inhibitor of IL-6 trans-signaling, sgp130Fc." (PMID 31694340, 2019). "The direct involvement of the metalloprotease ADAM17 in inflammation and colon cancer development has been recently shown in several mouse studies." (PMID 31060243, 2019). "In colon carcinoma cells, EpEX induced mild proliferation and regulated proteolysis of intact EpCAM molecules through the activation of ADAM17 and γ-secretase." (PMID 30261040, 2018). "We previously reported that a cytosolic domain (CTF2) of PTK7 generated by sequential cleavage by ADAM17 and γ-secretase translocates into nucleus and enhances oncogenic phenotype of colon cancer cells." (PMID 27689325, 2016). "In order to study the potential role of ADAM17 in the growth and progression of colon tumors we generated several MC38CEA colon carcinoma cell lines with stably silenced ADAM17 expression via transfection with ADAM17 shRNA coding vector." (PMID 23251384, 2012). "Here we show, using MC38CEA murine colon carcinoma model, that ADAM17 also regulates tumor angiogenesis and cytokine profile." (PMID 23251384, 2012). "To explore whether HDAC6 could affect ADAM17 expression and its activity, we measured the levels of the protein expression of ADAM17 and the cutting substrate peptides in colon cancer cells." (PMID 36270986, 2022).
colon carcinoma (continued). "Therefore, we confirmed that HDAC6 affects sIL-6R release in colon cancer cells by regulating the activity of ADAM17." (PMID 36270986, 2022). "Indeed, upregulation of ADAM17 and downregulation of mIL-6R were observed in a colon cancer model and in colon cancer patients, leading to increased cleavage of the mIL-6R and release of the sIL-6R from the tumor cells." (PMID 36551971, 2022). "The deletion of ADAM17 specially reduced the secretion of EMT-related cytokine in colon cancer." (PMID 33005106, 2020). "Previous studies have shown that ADAM17 is upregulated in colon tumor tissue." (PMID 33143292, 2020). "In the future, studies evaluating ADAM17 function in colon cancer development and how interference with ADAM17 function might be beneficial, have to be performed in the respective animal models." (PMID 31060243, 2019). "Especially within pathological pathways, as discussed here for colon cancer, it is important to fully understand activation but also impairments in ADAM17 function, which might provide us with potential new therapeutic strategies in the future." (PMID 31060243, 2019). "We therefore speculated that IL-6 trans-signaling initiated by the EGF-R mediated IL-6 secretion and the ADAM17-mediated IL-6R shedding might contribute to colon cancer formation in the APCmin/+ model." (PMID 31694340, 2019). "Interestingly, by using Tspan8-deficient HT29 colon carcinoma cells, we observed that while Tspan8 promoted cleavage of the ADAM17 substrate TNF α, it did not alter ADAM17-mediated shedding of TNFR1." (PMID 36078095, 2022). "Probably the cellular level of ADAM17 may augment malignant potential of colon carcinoma cells by increasing their motility and expression of proangiogenic factors, while at the tissue level it enhances angiogenesis and affects the cross talk between tumor cells and immune system." (PMID 27110571, 2016). "Our findings imply that at the cellular level ADAM17 may augment malignant potential of colon carcinoma cells by increasing their motility and expression of pro-angiogenic factors while at the tissue level enhances angiogenesis and affects the cross-talk between tumor cells and immune system." (PMID 23251384, 2012). "Therefore, we used EpAb2-6 to block the function of EpEX in colon cancer cells and analyzed the phosphorylation levels of HGFR, AKT, FAK, GSK3β, ERK, ADAM17, and presenilin 2 in HCT116 cells." (PMID 37543570, 2023). "Moreover, co-expression of ADAM17 and activated EGFRs, while not always proportional, suggests a role for ADAM17 in colon carcinoma growth and angiogenesis." (PMID 36572816, 2023). "In addition, ADAM17 also promotes STAT3 activation by induction of EGFR/IL-6 transduction signaling pathways, which ultimately lead to tumor progression; inhibition of the ADAM17/IL-6/STAT3 signaling axis significantly attenuated the growth of colon cancer cells." (PMID 36466812, 2022). "It has been recently shown that in the absence of ADAM17, the main protease for EGF-R ligand processing, colon cancer formation is largely abrogated." (PMID 31694340, 2019). "The situation in which the pro-tumorigenic potential of ADAM17-expressing cells is not correlated with increased cell proliferation, is not limited to MC38CEA colon carcinoma." (PMID 23251384, 2012).
Obesity (29 papers, 2011 to 2025). Accumulation of substantial excess body fat. "In experimental studies, treatment with the ADAM17 inhibitor Marimastat improved surrogate markers for insulin sensitivity and reversed steatosis in mouse models of diet-induced obesity and leptin deficiency." (PMID 38963109, 2024). "Even a causal relationship between increased ADAM17 and obesity was suggested from the knocking out of Adam17 in mice, which leads to an extremely lean phenotype due to hypermetabolism." (PMID 36009555, 2022). "Our results abrogate for a partial blocking of the inflammatory and fibrotic processes induced by ADAM17-related pathways as adjuvant treatment for renal pathologies associated to obesity and high glucose levels." (PMID 34884897, 2021). "In this study, we show that p38 activation associated with obesity directly impacts on Adam17 expression in DC-restricted progenitors." (PMID 32184787, 2020). "Importantly, persistent TMPRSS2 and ADAM17 expression was shown, even after significant weight loss, reflecting the long-lasting impact of obesity on adipose tissue biology." (PMID 40806445, 2025). "However, what role this intriguing interacting partner of ADAM17 plays in the vasculature and how it functions in the pathologies of obesity and associated CVDs, are exciting questions that are only beginning to be elucidated." (PMID 33330676, 2020). "A clinical study on centripetal obesity further confirmed that obesity, particularly when fat is predominantly deposited around the abdominal area, is associated with the cleavage of MERTK by ADAM17 to produce soluble MERTK." (PMID 40458640, 2025). "Both TMPRSS2 and ADAM17 protein levels increase in older women with obesity, when compared to controls (p = 0.0013 and p = 0.0274, respectively), and do not differ significantly from middle-aged individuals with prior obesity." (PMID 40806445, 2025). "Obesity is expected to hinder efferocytosis due to ADAM17-mediated cleavage of the MER tyrosine kinase receptor, producing soluble MER (sMER) that disrupts MERTK binding to cell death markers." (PMID 38550672, 2024). "Regarding tissue influence, visceral adipose tissue (VAT) was the only tissue to increase ADAM17 activity in response to the development of obesity." (PMID 38963109, 2024). "Previous studies showed that circulating levels of the extracellular domain of ADAM17 were higher in individuals with metabolic syndrome, type 2 diabetes and obesity." (PMID 37958866, 2023). "While numerous studies have dissected the role(s) of ADAM17 in inflammation and growth control, very few studies have focused on the role of ADAM17 in energy balance and obesity." (PMID 37121509, 2023). "We show that deletion of ADAM17 in adipocytes is sufficient to elevate energy expenditure under steady-state conditions and in obesity by increasing adipose tissue thermogenesis." (PMID 37121509, 2023). "Evidence in humans and rodents indicates that aging and obesity cooperatively increase vascular endothelial ADAM17 activity and the release of soluble TNFalfa by adipose tissue cells." (PMID 36009555, 2022). "The relationship between TNFα and ADAM17 levels and obesity is important because ADAM17 is responsible for the biological activity of TNFα." (PMID 36286024, 2022). "Obesity impairs the proliferation of DC-restricted progenitors via Adam17-p38 MAPK-dependent pathway, changes in DC precursors and DCs elicit an impaired immune response in allergic asthma." (PMID 36051916, 2022). "Our results propose ADAM17 as a potential therapeutic target and opens an interesting line of research as obesity and type 2 diabetes are increasing worldwide." (PMID 35008648, 2021). "The inhibitor, TIMP-3 was found to be down-regulated in adipose tissue/obesity and this correlated with an increase in ADAM17." (PMID 33904577, 2021). "Endothelial Adam17 knockout male mice and their controls were fed a high-fat diet, to induce obesity, or standard rodent chow, for 22 weeks." (PMID 35008648, 2021).
Obesity (continued). "Instead, glomerular hypertrophy and mesangial matrix expansion induced by high blood glucose levels and obesity condition were reduced in Adam17 knockout mice." (PMID 34884897, 2021). "Collectively, these results demonstrate that Adam17-p38 MAPK axis is tightly coupled to proliferation in DC-restricted progenitors in obesity." (PMID 32184787, 2020). "Shedding of ACE2Increased shedding of ACE2 from different tissues (including adipose tissue demonstrating high expression of this enzyme in obesity and T2D) induced by ADAM17 leads to re-distribution of ACE2 in the body and its accumulation in the lungs." (PMID 32930095, 2020). "We show that diet-induced obesity impairs proliferation of DC-restricted progenitors via Adam17-p38 MAPK-dependent pathway." (PMID 32184787, 2020). "Diet-induced obesity generates both quantitative increases in CDPs and cell surface expression of Adam17." (PMID 32184787, 2020). "Altogether, these results indicate that a tight control of Adam17 expression is critical to dysregulation of p38 MAPK signaling particularly in obesity, and show that Adam17 is one of the key determinants of DC-restricted progenitor expansion." (PMID 32184787, 2020). "In obesity, we show that Adam17 plays a regulatory role contributing to reinforce p38 MAPK activation and proliferation of DC-restricted progenitors." (PMID 32184787, 2020). "As such, these results further show that HFD is a key contributor to the dysregulation of Adam17 expression and is an obesity-response gene in DC-restricted progenitors." (PMID 32184787, 2020). "Molecularly, we establish that a disintegrin and metallopeptidase domain 17 (Adam17) is a key regulator of DC-restricted progenitors expansion and p38 activation in obesity." (PMID 32184787, 2020). "Moreover, the expression of TMPRSS2 and ADAM17 remains unchanged in individuals with previous obesity." (PMID 40806445, 2025). "Moreover, the upregulation of ADAM17, frequently observed in obesity, promotes ACE2 shedding and TNF release, further aggravating inflammation." (PMID 41562075, 2025). "Inactivation of ADAM17 suppressed high-fat diet (HFD) induced obesity, insulin resistance, hepatosteatosis, and adipose tissue remodeling in mice, with increased energy expenditure, suggesting an essential role for ADAM17 in the development of obesity-induced metabolic disorders." (PMID 38963109, 2024). "In addition to PS, other factors involved in ADAM17 regulation in obesity should also be considered, as previous research has shown that obesity is characterized by a deficiency of TIMP3 in white adipose tissue and liver, resulting in elevated ADAM17 levels." (PMID 38550672, 2024). "•ADAM17 ablation protects from obesity and improves metabolic health." (PMID 37121509, 2023). "AT-expressed ADAM17 activation in development of coronary microvascular dysfunction in obesity." (PMID 36359402, 2022). "In the present study we aimed to evaluate whether conditional Adam17 deletion in endothelial cells is able to protect different renal structures from the deleterious effects of obesity-mediated inflammation." (PMID 35008648, 2021). "To explore in more detail the molecular mechanisms involved in renal injury in the obesity mouse model with tubular Adam17 deletion, we analyzed the gene expression of cortical NADPH oxidase 4 (Nox4) and phosphorylated Dynamin-Related Protein (pDRP1) expression as markers of oxidative stress." (PMID 34884897, 2021). "A similar effect was found with Adam17 inhibitor, suggesting that proliferation of DC precursors could be regulated by Adam 17 activation in obesity." (PMID 32184787, 2020). "Therefore, as a novel ADAM17-shed adipokine, Semaphorin 4B could be a promising candidate for the development of new therapeutic strategies to treat obesity." (PMID 37121509, 2023).
Obesity (continued). "Similarly, in another study, mice with a heterozygous deletion of ADAM17 were protected from obesity (by elevating their energy expenditure in response to high-fat diet) and its associated metabolic dysregulation, such as glucose intolerance and insulin insensitivity." (PMID 37121509, 2023). "As increased ADAM17 expression is correlated with insulin resistance, it is likely that decreasing ADAM17 activity via various therapeutic strategies may increase insulin sensitivity and ultimately have a beneficial effect on obesity." (PMID 33904577, 2021). "Therefore, the blockage of ADAM17 could be a potential therapeutic target for patients with obesity and/or hyperglycemia." (PMID 34884897, 2021). "ACE2, TMPRSS2, ADAM17, and NRP1 are more expressed in visceral AT, with obesity significantly influencing their protein expression." (PMID 40806445, 2025). "In women with previous obesity, ACE2 and NRP1 levels decreased, while TMPRSS2 and ADAM17 remained unchanged." (PMID 40806445, 2025). "ADAM17 expression in subcutaneous AT seems to depend simultaneously on ageing and obesity, since the isolated factors did not significantly influence ADAM17 protein levels." (PMID 40806445, 2025). "Interestingly, here, a different pattern of expression of the receptors (ACE2 and NRP1) and co-receptors (ADAM17 and TMRPSS2) with obesity and ageing is reported." (PMID 40806445, 2025). "It is, however, unclear if, over a longer period, these patients would reach the levels of TMPRSS2 and ADAM17 observed in individuals without obesity." (PMID 40806445, 2025). "Markers important in obesity and efferocytosis (e.g., PS, ADAM17, TNF-α, and sMER) were observed between the obese and nonobese groups, opening the opportunity to identify potential biomarkers for therapeutic exploration." (PMID 38550672, 2024). "Thus, expression patterns of three genes (IFITM3, ADAM17, IFNE) in PBCs at the time of hospital admission marked both disease evolution severity and obesity status, especially in male patients." (PMID 36009555, 2022). "ADAM17, IFITM3, IL6 and IFNE were more highly expressed in PBCs of patients with obesity." (PMID 36009555, 2022). "Finally, we demonstrate that Adam17 is one of the key regulators of p38 MAPK activation and is required for the proliferation of DC-restricted progenitors in obesity." (PMID 32184787, 2020). "Therefore, the observed variations in ACE2, ADAM17, and NRP1 expression are primarily attributable to obesity itself rather than to confounding effects from underlying conditions or treatments." (PMID 40806445, 2025). "To investigate if this novel pathway mediated by Sema4B cleavage by ADAM17 in adipocytes could have an impact in human obesity, we measured the mRNA levels of SEMA4B, PLEXIN (PLXN)B1 and 2, NEUROPILIN (NRP) 1 and 2, ADAM17, and of its known critical regulator iRHOM2 in human adipose tissues." (PMID 37121509, 2023). "Interestingly, ADAM17 and IFITM3 mRNA levels were maximal in the patients that became critically ill during hospitalization (one-way ANOVA, post-hoc analysis) and in patients with obesity (with BMI > 30) (one-way ANOVA, post-hoc analysis)." (PMID 36009555, 2022). "The lack of differences in the gene expression of placental ADAM17, PLAU, and IGF2 between the three groups suggests that these genes would not be affected by obesity." (PMID 37408866, 2023). "In addition, liver ADAM17 activity and serum soluble TNF-α were significantly decreased in AlbT3 mice compared to wt, suggesting that, as expected, the liver overexpression of TIMP3 is able to regulate ADAM17 functions, rather than expression, during obesity." (PMID 28751722, 2017).